RARRES2 (retinoic acid receptor responder 2)
Description:
Adipocyte-secreted protein (adipokine) that regulates adipogenesis, metabolism and inflammation through activation of the chemokine-like receptor 1 (CMKLR1). Also acts as a ligand for CMKLR2. Can also bind to C-C chemokine receptor-like 2 (CCRL2), but with a lower affinity than it does to CMKLR1 or CMKLR2. Positively regulates adipocyte differentiation, modulates the expression of adipocyte genes involved in lipid and glucose metabolism and might play a role in angiogenesis, a process essential for the expansion of white adipose tissue. Also acts as a pro-inflammatory adipokine, causing an increase in secretion of pro-inflammatory and prodiabetic adipokines, which further impair adipose tissue metabolic function and have negative systemic effects including impaired insulin sensitivity, altered glucose and lipid metabolism, and a decrease in vascular function in other tissues. Can have both pro- and anti-inflammatory properties depending on the modality of enzymatic cleavage by different classes of proteases. Acts as a chemotactic factor for leukocyte populations expressing CMKLR1, particularly immature plasmacytoid dendritic cells, but also immature myeloid DCs, macrophages and natural killer cells. Exerts an anti-inflammatory role by preventing TNF/TNFA-induced VCAM1 expression and monocytes adhesion in vascular endothelial cells. The effect is mediated via inhibiting activation of NF-kappa-B and CRK/p38 through stimulation of AKT1/NOS3 signaling and nitric oxide production. Its dual role in inflammation and metabolism might provide a link between chronic inflammation and obesity, as well as obesity-related disorders such as type 2 diabetes and cardiovascular disease. Exhibits an antimicrobial function in the skin.
Synonyms: TIG2; HP10433
Tractability: Small molecule: a structure with a bound ligand is known. Antibody: its Gene Ontology location is reachable by antibodies, with high confidence; UniProt places it where antibodies can reach, with medium confidence; UniProt predicts a signal peptide or a membrane-spanning region. PROTAC: ubiquitination databases record sites on it.
Gene: Protein-coding gene on chromosome 7 (150,338,314 to 150,342,144, reverse strand). Ensembl gene ENSG00000106538.
Subcellular location: Secreted
Pathways (Reactome):
Hemostasis: Platelet degranulation
Gene Ontology:
Molecular function: protein binding; signaling receptor binding
Biological process: antifungal humoral response; antifungal innate immune response; defense response to Gram-negative bacterium; defense response to Gram-positive bacterium; embryonic digestive tract development; innate immune response; insulin receptor signaling pathway; positive regulation of macrophage chemotaxis; positive regulation of protein phosphorylation; retinoid metabolic process; positive regulation of chemotaxis; positive regulation of fat cell differentiation; regulation of chemokine activity; regulation of inflammatory response; regulation of lipid catabolic process; cellular response to insulin stimulus; developmental process; inflammatory response; positive regulation of systemic arterial blood pressure; regulation of insulin receptor signaling pathway; response to activity; response to caloric restriction; response to nutrient levels
Cellular component: extracellular matrix; extracellular region; G protein-coupled receptor complex; decoy receptor complex; platelet dense granule lumen
Genetic constraint (gnomAD): Loss-of-function variants: 12 observed, 15.07 expected, observed/expected ratio (o/e) 0.8, 90% interval 0.51 to 1.29. The upper end of that interval is the gene's LOEUF score, 1.29, which puts it in group 5 of 6, group 1 being the genes least tolerant of losing a copy. Missense variants: 220 observed, 189.2 expected, observed/expected ratio (o/e) 1.16, 90% interval 1.04 to 1.3. Synonymous variants: 82 observed, 72.07 expected, observed/expected ratio (o/e) 1.14, 90% interval 0.95 to 1.37.
Homologues: Orthologues: chimpanzee RARRES2 (99% identical), macaque RARRES2 (95% identical), pig RARRES2 (83% identical), dog RARRES2 (81% identical), guinea pig RARRES2 (79% identical), rabbit RARRES2 (69% identical), rat Rarres2 (66% identical), mouse Rarres2 (63% identical), tropical clawed frog rarres2 (32% identical).
Diseases named in the same sentence as RARRES2 in open-access papers:
RARRES2 is named in the same sentence as 88 diseases in open-access papers, as found by Europe PMC text mining. Sharing a sentence is not in itself a finding about the gene and the disease. The quoted sentences say what the papers report.
Obesity (20 papers, 2014 to 2025). Accumulation of substantial excess body fat. "Chemerin (RARRES2), an adipokine and chemoattractant factor, has been implicated in obesity, inflammatory disorders, and cancer." (PMID 37762031, 2023). "In the case of the second most significant gene in our study, RARRES2, the low expression of its homolog was found to be a characteristic of the astrocyte fraction in the mouse brain and it was associated with obesity and metabolic disease in humans." (PMID 35288843, 2022). "RARRES2 has been associated with inflammation, obesity, and the metabolic syndrome." (PMID 35159232, 2022). "While previous studies of RARRES2 mainly focused on autoimmune diseases and obesity, our study reveals a role of RARRES2 in lipid metabolism in BCBrM." (PMID 37491281, 2023). "RARRES-2, also known as chemerin, is involved in adipogenesis, regulation of inflammation and metabolism, and is considered a potential link between obesity and development of insulin resistance." (PMID 34480568, 2022). "The RARRES2/CMKLR1 system is considered to be a potential actor underlying the regulation of glucose and fat metabolism linked to obesity in humans and mice." (PMID 30777067, 2019). "In patients with T2DM (with grade II and III obesity), the expression of the RARRES2 gene increased in the GO and SAT." (PMID 30871547, 2019). "The aim of the present study was to test the impact of common genetic variations in ADIPOQ, RARRES2, and PPARGC1 on obesity-related traits and susceptibility in a sample of adult subjects from Rio de Janeiro, Brazil." (PMID 28947843, 2017). "This study investigated the relationship between common variants of adiponectin (ADIPOQ), retinoic acid receptor responder 2 (RARRES2), and peroxisome proliferator-activated receptor-γ coativator-1 (PPARGC1) and obesity-related traits and susceptibility." (PMID 28947843, 2017). "The largest network included 20 proteins and was predicted to be involved in tissue morphology, inflammatory response and cardiovascular diseases including proteins encoded by genes already associated with obesity (INS, LEP, SERPINE1, IL1RAP, and RARRES2)." (PMID 29234017, 2017). "Evidence suggests that the RARRES2-CMKLR1 axis may be involved in regulating metabolic processes related to obesity, influencing glucose and fat metabolism in humans and murine models." (PMID 41007912, 2025). "RARRES2 belongs to the adipokine family, and this protein may be a link between OA and obesity (its upregulation is confirmed in both disorders)." (PMID 36233118, 2022). "In contrast, RARRES2 serves as a biomarker of obesity and metabolic syndrome in humans." (PMID 32005146, 2020). "If chemerin does provide some protection against obesity, it does not seem that this is directly linked to increased expression of RARRES2 mRNA in perigenital adipose tissue." (PMID 25699203, 2015). "However, mtDNA copy number in the SAT was negatively associated with the expression of the RARRES2 gene in patients without T2DM (with grade III obesity) (r = − 0.84, p < 0.05; r2 = − 0.69, p < 0.05)." (PMID 30871547, 2019). "The expression level of the TNF-α gene was positively correlated with the expression level of the RARRES2 gene in the GO in patients with T2DM (with grade I and II obesity) (r = 0.66, p < 0.05 and r = 0.67, p < 0.05, respectively)." (PMID 30871547, 2019). "Another study of 150 participants (100 with obesity and 50 without obesity) in the Netherlands found that SELE, IGFBP1 and RARRES2 were significantly different between participants with obesity versus without obesity." (PMID 38548792, 2024). "Although the CMKLR1 mRNA level in fat tissue is not changed by obesity, the local RARRES2 mRNA expression in visceral and subcutaneous adipose tissue is significantly increased in obese individuals." (PMID 29848608, 2018). "In the patients without T2DM (with grade I and II obesity), the relative expression levels of TNF-α and RARRES2 genes in the GO were correlated." (PMID 30871547, 2019).
metabolic syndrome (11 papers, 2014 to 2024). A cluster of metabolic risk factors for CARDIOVASCULAR DISEASES and TYPE 2 DIABETES MELLITUS. "Polymorphisms in the gene encoding chemerin (retinoic acid receptor responder 2, RARRES2) were linked to increased systemic chemerin levels, visceral fat mass, and a higher incidence of the metabolic syndrome." (PMID 30841637, 2019). "SNP rs17173608 of RARRES2 can increase the risk of suffering from metabolic syndrome and SNP rs10278590 and rs 10282458 can promote formation of visceral fat to increase the risk of T2DM." (PMID 27446956, 2016). "The RARRES2 rs17173608 SNP had been associated with metabolic syndromes and obesity." (PMID 34071097, 2021). "Studies have reported the pleiotropic effects of RARRES2 SNPs, including a varying adiposity status, visceral fat mass, metabolic syndrome, and polycystic ovary syndrome." (PMID 29720894, 2018). "Another study has showed that serum RARRES2 level was correlated with metabolic syndrome indicators positively including body mass index, waist-hip ratio, and blood pressure." (PMID 27446956, 2016). "Variants of retinoic acid receptor responder 2 (RARRES2), the gene encoding chemerin, have been demonstrated to be associated with increased chemerin levels, visceral fat mass in nonobese individuals, and increased incidence of metabolic syndrome." (PMID 37831337, 2024). "Notably, variants in retinoic acid receptor responder 2 (RARRES2), the gene encoding chemerin, have been shown to be associated with increased visceral fat mass in non-obese subjects and with increased incidence of the metabolic syndrome." (PMID 25521368, 2014). "However, the relationships between RARRES2, inflammation, metabolic syndromes, insulin resistance, and CAD have not been completely elucidated." (PMID 34071097, 2021).
breast carcinoma (8 papers, 2019 to 2025). "Of note, we mainly focused on TNBC in this study, and the association between RARRES2 and BCBrM in other breast cancer subtypes needs further investigation." (PMID 37491281, 2023). "Collectively, these findings suggest that the expression of RARRES2 is decreased specifically in BrM of breast cancer, highlighting a potential association between RARRES2 downregulation and BrM." (PMID 37491281, 2023). "In summary, our current study focused on BrM, the clinical dilemma of breast cancer, and identified the specific association between RARRES2 and BCBrM." (PMID 37491281, 2023). "RARRES2 overexpression significantly suppressed BrM following both intracranial and intracardiac injection, while RARRES2 knockdown significantly promoted breast cancer cell proliferation and invasion." (PMID 39450411, 2024). "It did however significantly enhance macrophage migration, highlighting the potential role of RARRES2-CMKLR1 signaling in breast cancer." (PMID 37726308, 2023). "Analysis of GSE14020 revealed that the level of RARRES2 was notably lower in the breast cancer that metastasized to brain than that to bone and lung (P = 0.019, P < 0.001)." (PMID 37491281, 2023). "Based on these observations, it is reasonable to propose that RARRES2-downregulated breast cancer cells decreased cellular level of TAGs to adapt to the low-TAG microenvironment of the brain." (PMID 37491281, 2023). "Taken together, these findings strongly suggest that RARRES2 plays a crucial role in BCBrM, as high levels of RARRES2 impede the process of BrM in breast cancer." (PMID 37491281, 2023). "Our results not only add new insights to the current understanding of lipid metabolism and breast cancer BrM, but also suggest potential therapeutic targeting of RARRES2 as an intervention for this life-threatening disease." (PMID 37491281, 2023). "Here, we analyzed the two largest breast cancer datasets with data for RARRES2 that were curated within the Oncomine database." (PMID 31139180, 2019). "Furthermore, we extended our investigation to identify RARRES2 co-expressed genes in the single-cell transcriptome data of breast cancer and BrM cancer epithelial cells respectively, and explored the biological processes regulated by RARRES2." (PMID 37491281, 2023). "This led us to speculate that the decreased expression of RARRES2 in breast cancer cells that have metastasized to the brain may be an adaptation to the brain microenvironment." (PMID 37491281, 2023). "Additionally, we then examined the expression of RARRES2 using the MetMap data (GSE148283) and found a significant downregulation of RARRES2 in the breast cancer cells metastasized to the brain compared to metastasis in the liver (P = 0.0003)." (PMID 37491281, 2023). "Thus, across multiple datasets and analytical expression methods, chemerin/RARRES2 was consistently down-regulated in malignant breast cancer samples vs. controls, and reduced chemerin/RARRES2 expression was correlated with poor survival outcome." (PMID 31139180, 2019). "Collectively, we provide a pathogenic mechanism linking RARRES2 and lipid metabolic reprogramming in the development of BrM in breast cancer, with the anticipation that the RARRES2-dependent metabolic functions may serve as biomarkers or therapeutic targets for BCBrM in TNBC." (PMID 37491281, 2023). "After confirming down-regulation of RARRES2 mRNA in additional human studies, we then set out to favorably modulate chemerin expression in the EMT6 mammary carcinoma model." (PMID 31139180, 2019). "We find that in breast cancer patients, RARRES2 is expressed specifically in CAFs - it is not expressed in normal fibroblasts or in any other cell type in the breast TME." (PMID 37726308, 2023).
breast carcinoma (continued). "To investigate whether interference with RARRES2-mediated lipid metabolic reprogramming affects the malignant phenotype of breast cancer cells, we conducted experiments using etomoxir, a CPT1 inhibitor, on MDA-MB-231 cell line with altered RARRES2 expression." (PMID 37491281, 2023). "We conclude that RARRES2, identified through our in-vitro circuit approach, mediates CAF signaling to TAMs in mouse models of breast cancer and in human disease, and may serve as a therapeutic target for future exploration." (PMID 37726308, 2023). "Finally, we show significantly reduced levels of RARRES2 mRNA in human breast cancer samples compared to matched normal tissues." (PMID 31139180, 2019).
type 2 diabetes (8 papers, 2015 to 2023). "Stimulated by retinoic acid gene homolog 6 (STRA6) and retinoic acid receptor responder 2 (RARRES2) are candidate genes involved in the pathogenesis of type 2 diabetes mellitus (T2DM)." (PMID 27446956, 2016). "However, we note that other PPARγ agonists have been reported to reduce RARRES2 mRNA levels in epididymal and mesenteric adipose tissue when administered to mice, and plasma chemerin levels when administered to patients with type 2 diabetes." (PMID 25699203, 2015).
ovarian carcinoma (6 papers, 2009 to 2025). A malignant neoplasm originating from the surface ovarian epithelium. "Increased levels of GRN and RARRES2 in plasma from ovarian cancer patients in both the early and the late stage cases are a novel findings in this study." (PMID 19936259, 2009). "Chemerin, also known as retinoic acid receptor responder 2 (RARRES2), is one of the adipokines suspected of exerting an influence on ovarian cancer." (PMID 40076482, 2025). "Chemerin (RARRES2 [retinoic acid receptor responder 2] and TIG2 [tazarotene induced gene 2]), is purified from the ascetic fluids of ovarian cancer patients and has been shown to be a natural ligand for G protein-coupled receptor-1 (GPR-1) and chemokine C-C motif receptor-like-2 (CCRL-2)." (PMID 29190935, 2017). "RARRES2 levels negatively, whereas CMKLR1 levels positively influenced both OS and progression-free survival (PFS) of ovarian cancer patients, and GPR1 and CCRL2 levels did not affect patients’ OS or PFS." (PMID 36009457, 2022).
psoriasis (6 papers, 2020 to 2026). An autoimmune condition characterized by red, well-delineated plaques with silvery scales that are usually on the extensor surfaces and scalp. "Our group has also identified chemerin/RARRES2, the natural ligand of Chemerin Receptor 1, as a new chemotactic factor for human pDCs transiting toward lymphoid tissues and inflamed skin (i.e. lupus erythematosus and psoriasis)." (PMID 39020402, 2024).
melanoma (5 papers, 2012 to 2025). A malignant, usually aggressive tumor composed of atypical, neoplastic melanocytes. "Finally, in two independent clinical cohorts of melanoma patients, retention of high RARRES2 (a gene encoding the chemoattractant chemerin) expression correlated with better clinical outcomes." (PMID 23269924, 2012). "Another study analysed hypermethylation of RASSF1A and RARRES2 in 37 melanoma patients with clinically positive lymph nodes." (PMID 34441278, 2021). "In most tumor entities, chemerin/RARRES2 is down-regulated compared to normal tissue, e.g., in tumors of the breast, melanoma, lung, prostate, liver, adrenal, and in melanoma, and this decrease of chemerin expression has been suggested to be part of the tumor ́s immune escape." (PMID 36900088, 2023). "TIG2 (also known as chemerin, gene name RARRES2) plays an important immune regulatory role in melanoma suppression, primarily by recruiting and activating immune cells to exert antitumor effects." (PMID 40699636, 2025). "Hypermethylation in RARRES2 was 70% in both primary and metastatic melanoma, but RASSF1A, DAPK and MGMT had significantly lower hypermethylation in primary melanoma versus metastatic melanoma." (PMID 34441278, 2021). "Similarly, the most hypermethylated gene in melanoma cell lines was RASSF1A (80%), followed by RARRES2 (53%) and MGMT (27%)." (PMID 34441278, 2021).
Hypertension (4 papers, 2016 to 2023). The presence of chronic increased pressure in the systemic arterial system. "Like Ptgs2, Rarres2 is also known to regulate inflammation and has been linked with hypertension, a known risk factor of aortic valve stenosis." (PMID 29740591, 2018).
Insulin resistance (4 papers, 2019 to 2023). Increased resistance towards insulin, that is, diminished effectiveness of insulin in reducing blood glucose levels. "On the other hand, PCOS women have elevated levels of RARRES2, which is associated with insulin resistance and inflammation." (PMID 37626836, 2023). "rs17173608 is a RARRES2 gene variant, and to the best of our knowledge, this is the first study to associate rs17173608 with demographic and clinical factors of insulin resistance and severity of CAD." (PMID 34071097, 2021). "In humans, levels of RARRES2 mRNA increased in maternal adipose tissue during normal gestation possibly contributing to the increase of maternal circulating RARRES2 concentrations that are associated with maternal body mass index and insulin resistance." (PMID 30777067, 2019).
polycystic ovary syndrome (4 papers, 2018 to 2024). A disorder that manifests as multiple cysts on the ovaries. "In rat, treatment with dihydrotestosterone induces polycystic ovarian syndrome associated with metabolic disorders and elevated ovarian RARRES2 levels." (PMID 30777067, 2019).